INS (insulin)
Diseases named in the same sentence as INS in open-access papers (continued):
Sharing a sentence is not in itself a finding about the gene and the disease.
diabetic foot ulcers (31 papers, 2009 to 2025). "Local injectable insulin was more effective in the short-term healing of diabetic foot ulcers than topical phenytoin and regular saline." (PMID 36407151, 2022). "With this background, we conducted the present study among diabetic patients to compare the efficacy of diabetic foot ulcer management between local injectable insulin, topical phenytoin, and normal saline." (PMID 36407151, 2022). "The current study, which lasted a year in a tertiary care hospital, found that local injectable insulin heals diabetic foot ulcers more rapidly than local topical phenytoin, which is superior to the standard treatment of using normal saline." (PMID 36407151, 2022). "According to the current study, local injectable insulin has higher efficacy than local phenytoin, which is also comparatively more effective than normal saline in treating diabetic foot ulcers." (PMID 36407151, 2022). "The rates of insulin treatment, duration of insulin treatment, and total daily insulin doses were similar between patients with diabetic foot ulcers who had low and normal handgrip strength (p = 0.195, p = 0.504, and p = 0.355, respectively)." (PMID 36945977, 2022). "Our results suggest that effective treatment of diabetic foot ulcers can be achieved with a methyl cellulose-based insulin preparation (H3-INS)." (PMID 34452176, 2021). "The effect of combined insulin and dipeptidyl peptidase-4 inhibitor (DPP4i) therapy on major adverse cardiovascular events (MACEs) in patients with diabetic foot is unclear." (PMID 30349614, 2018). "Among the 19,791 patients with diabetic foot (mean age, 58.8 years [SD, 12.5]; men, 51.2%), 6466 received DPP4i-based therapy, 1925 received insulin-based therapy, and 11,400 received combined DPP4i and insulin therapy." (PMID 30349614, 2018). "Also, the composition of oral antidiabetics, the rates of insulin treatment, duration of insulin treatment, and total daily insulin doses were similar between patients with diabetic foot ulcers who had low and normal handgrip strength." (PMID 36945977, 2022). "It has been observed that male diabetic foot ulcer patients not on insulin therapy have increased risk of undergoing a major limb amputation." (PMID 33435942, 2021). "However a clear cut information on the indications for initiating insulin in diabetic foot ulcers have to be determined." (PMID 33435942, 2021). "Physicians can complete part of the physical examination via video, such as checking skin lesions and diabetic foot ulcers; examination of the symmetry of gait and facial lesions; skin abnormalities at the insulin injection site; and goiter (strong recommendation, C)." (PMID 33833798, 2021). "Thus, surgeons can opt for local insulin to treat diabetic foot ulcers." (PMID 36407151, 2022). "Most patients with diabetic foot were in the 50–59 year age group (31.0% in total and 30.0%, 33.1%, and 30.1% in the combined, DPP4i-based, and insulin-based groups, respectively), and most of the patients (57.6%) received combination therapy with a DPP4i and insulin." (PMID 30349614, 2018). "There is currently a great deal of research into the development of insulin (INS) carriers for topical therapy of chronic wounds, particularly in patients with diabetic foot ulcers." (PMID 39339083, 2024). "This strategy wouldhave immediate clinical implications, enabling healthcare providersto prescribe both insulin and metformin as part of an integrated treatmentplan for patients with nonhealing diabetic foot ulcers." (PMID 39296257, 2024). "Apart from the insulin signaling pathway, other pathways are involved in this ailment including the canonical Wnt (wingless-type MMTV integration site family) signaling pathway, which plays a role in the healing of diabetic foot ulcer, and regeneration of insulin-producing pancreatic cells." (PMID 26262991, 2015).
hypertrophic cardiomyopathy (31 papers, 2012 to 2025). A condition in which the myocardium is hypertrophied without an obvious cause. "For example, prelamin‐A/C helps to maintain the volume and strength of skeletal muscle 45 and when its gene is mutated, it directly induces severe aortic stenosis and hypertrophic cardiomyopathy, along with atypical fat distribution and insulin resistance." (PMID 28402037, 2017). "For example, the significant modules included arrhythmogenic right ventricular cardiomyopathy, hypertrophic cardiomyopathy, and insulin secretion." (PMID 36230385, 2022). "Several KEGG pathways were obtained for differentially phosphorylated proteins in (5/6Nx + NS)/(Sham + NS) comparison groups, such as insulin signaling pathway, adipocytokine signaling pathway, hypertrophic cardiomyopathy and focal adhesion." (PMID 27775022, 2016). "A total of 433 DEGs representing known pathways for calcium signaling, PI3K/AKT signaling, RAS signaling, MAPK signaling, PPAR signaling, insulin secretion, and dilated and hypertrophic cardiomyopathy signaling were upregulated in Ob/Ob mice bearing Tet2–/– cells compared with WT recipient mice." (PMID 37071471, 2023). "When analyzing the differential methylation signature in the non-dilated aorta we found that differentially methylated genes were related to insulin- and adipokine signaling, and hypertrophic cardiomyopathy, which may seem surprising." (PMID 29426841, 2018). "There were 6 significantly enriched pathways (Fisher Exact Probability Test, p < 0.05), including Adipocytokine signaling pathway, Insulin signaling pathway, Hypertrophic cardiomyopathy (HCM), Bacterial invasion of epithelial cells, Viral carcinogenesis, and Phagosome." (PMID 26150313, 2015). "Other ontology terms included insulin signaling (FDR q = 5.59e-6), hypertrophic cardiomyopathy (FDR q = 3.38E-5) and adipocytokine signaling (FDR q = 2.35e-3)." (PMID 29426841, 2018). "It participated in the mTOR signaling pathway, the adipocytokine signaling pathway, the regulation of autophagy, hypertrophic cardiomyopathy (HCM), and the insulin signaling pathway of the KEGG pathway in heat-pattern, RA patients but not in cold-pattern RA patients." (PMID 22536280, 2012). "The explanation behind the development of hypertrophic cardiomyopathy in those patients is not yet determined, but it is thought to be due to high insulin concentrations that act through the insulin-like growth factor-I (IGF-1) receptor, which is also present in the heart." (PMID 38773407, 2024).
left ventricular hypertrophy (31 papers, 2007 to 2025). Enlargement of the LEFT VENTRICLE of the heart. "Specifically, visceral adiposity is linked to increased inflammation, left ventricular hypertrophy, insulin resistance, and various cardiac dysfunctions, including diastolic and systolic left ventricular dysfunction." (PMID 38767042, 2024). "Increased TG/HDL ratio in obese children is associated with the development of eccentric left ventricular hypertrophy while increased BMI and insulin were associated with concentric left ventricular hypertophy." (PMID 32456629, 2020). "Based on the obtained results we showed that in obese children TG/HDL ratio was postively associated with eccentric left ventricular hypertrophy, and BMI and insulin levels are postively associated with concentric left ventricle hypertrophy." (PMID 32456629, 2020). "Although the physiological function of leptin is rather contradictory, as it is associated with left ventricular hypertrophy in hypertensive, insulin-resistant men, it also induces direct vasodilatation through distinct endothelial mechanisms." (PMID 25787668, 2015). "However, coadministration of rosiglitazone or pioglitazone with insulin has been shown to increase the risk of AEs such as weight gain, edema, and left ventricular hypertrophy, which can lead to HF." (PMID 39881876, 2024). "Genetically predicted BMI is associated with higher left ventricular hypertrophy and increased concentrations of triglycerides, glucose, insulin, and interleukin 6 (an inflammatory marker), which may contribute to the observed associations with CVD." (PMID 31195408, 2020). "Increased glycemia leads to elevated serum insulin levels, which in cardiac tissue, induces increased protein synthesis of cardiomyocytes and, consequently, left ventricular hypertrophy." (PMID 32032383, 2020). "Increased glycemia leads to elevated serum insulin levels, which in cardiac tissue induce elevated protein synthesis of cardiomyocytes and, consequently, left ventricular hypertrophy." (PMID 32032383, 2020). "Diets with high intakes of simple carbohydrates may result in increased heart exposure to insulin, which activates cardiac protein synthesis and may promote left ventricular hypertrophy." (PMID 32032383, 2020). "Furthermore, correcting elevations in intracellular calcium results in clinical improvements in blood pressure, insulin resistance, platelet aggregation, and left ventricular hypertrophy." (PMID 22905228, 2012). "The data presented demonstrate the ability of Ex(9‐39) to deleteriously impact both structural and functional properties of the aorta and carotid arteries and to induce left ventricular hypertrophy independent of changes in glucose or insulin." (PMID 29984491, 2018).
mood disorder (31 papers, 2011 to 2025). A cognitive disorder a disturbance in which the person's mood is hypothesized to be the main underlying feature. "Another function is the mediation of several pathways for insulin or serotonin, which are associated with mood disorders." (PMID 38138159, 2023). "A hyperdopaminergic state in the amygdala may underlie increased risk of mood disorder observed in insulin-resistant, diabetic rats." (PMID 40600014, 2025). "Intranasal insulin treatment has been linked with cognitive improvement in BD, and more recently, preliminary evidence has described pro-cognitive effects of metformin use in those with a mood disorder." (PMID 36243769, 2023). "Similarly, SERT-deficient mice fed a Western-style diet exhibited impaired brain insulin tolerance and abnormal expression of 5-HT receptor subtypes, suggesting that serotonergic deficiency may exacerbate both metabolic- and mood disorder-related phenotypes." (PMID 41244820, 2025). "Cobalt and chromium: Trivalent chromium salts improve insulin efficiency, control blood sugar, and regulate mood disorders." (PMID 39170573, 2024). "While metformin may alleviate depressive symptoms by improving insulin sensitivity, abrupt discontinuation in patients with mood disorders can destabilize their mental health." (PMID 41269930, 2025). "Impaired insulin signaling in the brain plays a role in mood disorders in patients with type 2 DM." (PMID 38275390, 2023).
liver failure (30 papers, 2012 to 2025). A liver disease characterized by the liver losing or has lost all of its function. "In the analysis of hepatic failure, DPP4is and acarbose were associated with a lower risk (HR: 0.71 [95% CI 0.51–1.00] and 0.72 [95% CI 0.52–1.00]) compared to insulin." (PMID 40836299, 2025). "We also found that insulin users had a higher risk of hepatic failure." (PMID 40836299, 2025). "Moreover, because insulin users in this study showed increased risks of major cardiovascular events, cirrhotic decompensation, and liver failure, these conditions may also increase the risk of death." (PMID 34118892, 2021). "A previous publication emphasized the significance of various factors in influencing triglyceride levels, including age, insulin dosage, and hepatic failure." (PMID 40142777, 2025). "Based on differences in the transcriptional and metabolic profile of the pHx and eHx models, dysregulated cholesterol metabolism and insulin resistance pathways were closely correlated to liver failure and individual death post-eHx." (PMID 37679685, 2023). "- Because insulin is metabolized in the liver and eliminated in the urine, insulin dosage needs to be adjusted in individuals with renal impairment and liver failure,- In patients with a history of hypoglycemic episodes, the dosage of insulin and blood glucose levels should be closely monitored." (PMID 39889198, 2025). "Hepatic insulin clearance is reduced in patients with liver failure, leading to an increase in glycosylation end products, hypoxia and hypoxia-induced factors, that reduce liver blood supply and inhibit liver regeneration, thus affecting the prognosis of patients." (PMID 35788251, 2022). "In the same way, it is known that preoperative increases in hepatic glycogen content through administration of insulin and glucose may have a protective effect against the development of postoperative liver failure." (PMID 28826408, 2017). "This may be related more to the severity of the disease than the treatment itself, as insulin is usually started when the disease cannot be managed by diet and oral medications alone or if there are contraindications for oral therapy, such as kidney or liver failure." (PMID 32962295, 2020). "Insulin users showed higher risks of all-cause mortality, HCC, decompensated cirrhosis, hepatic failure, and MACE than nonusers." (PMID 34118892, 2021). "The precise mechanism of impaired insulin activity among patients with liver failure has not been described." (PMID 22829443, 2013).
lung disease (29 papers, 2006 to 2025). "A secondary analysis discovered a significant interaction between aspirin use and insulin: aspirin was associated with lower rates of lung disease except among those taking both drugs where the prevalence is significantly higher." (PMID 35969698, 2022). "Because insulin levels play particular roles in lung diseases 35, rs7242 may also modulate the risk of RP by influencing insulin levels in cancer patients." (PMID 28211612, 2017). "Insulin therapy remains the cornerstone of treatment, especially in patients with advanced lung disease (FEV1 <60%) or when rapid glycemic control is necessary." (PMID 40519490, 2025). "This is further confirmed by the observation that metformin is considered a potential therapeutic agent in lung diseases, while insulin has been shown to exacerbate lung diseases." (PMID 39371928, 2024). "Under these conditions, adipose tissue becomes dysfunctional because it becomes less insulin responsive and secretes more pro-inflammatory adipokines, promoting macrophage infiltration and further aggravating insulin resistance and lung diseases." (PMID 35806353, 2022). "Recently, microbiota-derived EVs have been reported to regulate gut permeability through tight junction regulation, to induce insulin resistance in skeletal muscles, and to be present in patients with lung disease." (PMID 32825137, 2020). "Some possible confounding factors, like in utero exposure to antibiotics and in utero exposure to insulin, showed a significant increase in the use of drugs for pulmonary disease." (PMID 22815049, 2013). "In multivariate analysis, only insulin levels, pulmonary disease, and family history of CAD were independent predictors of BAC." (PMID 24058592, 2013). "In multivariate analysis, only insulin levels (odds ratio = 1.05 [95% confidence interval = 1.01, 1.08], p=0.010), pulmonary disease (5.07 [1.35, 19.050], p=0.016), and family history of CAD (0.38 [0.14, 1.00], p=0.050) were independent predictors of BAC." (PMID 24058592, 2013). "Because other factors were not different between the exposed and the unexposed groups, we did not correct for maternal use of insulin, and maternal use of drugs for pulmonary disease." (PMID 22815049, 2013). "KEGG analysis identified some pathways involved in aging, including insulin, AMPK, and FoxO signaling, among the top 50 pathways, but no lung disease-related pathways." (PMID 41463319, 2025).
nesidioblastosis (29 papers, 2007 to 2025). "Nesidioblastosis is a rare pancreatic disorder involving enlarged beta cells throughout the pancreas, causing elevated insulin production." (PMID 36248221, 2022). "Other causes are possible such as islet cell hyperplasia, nesidioblastosis or antibodies to insulin or to the insulin receptor." (PMID 31448019, 2019). "In four patients we found a significant rise of insulin levels obtained from all catheterized sites, which confirmed the diagnosis of nesidioblastosis." (PMID 39497809, 2024). "It was also once referred to as “nesidioblastosis” based on an early suggestion that the increased insulin secretion is secondary to budding of pancreatic islets observed in histological samples from patients with CHI." (PMID 37056678, 2023). "Functionally, the in vitro studies also confirmed that nesidioblastosis-derived islet cells have a higher basal insulin secretion, an overall higher insulin content, and express more insulin mRNA." (PMID 37371827, 2023). "A full workup excluded an insulinoma (including serum insulin and C-peptide monitoring, fasting test and pancreatic MRI) and the diagnosis of nesidioblastosis was established." (PMID 35716625, 2022). "Of note, prolonged IGFBP3/TMEM219 blockade with ecto-TMEM219 was associated with significant beta-cell expansion, which lead to a significant increase of both islet area and peripheral insulin levels, mimicking nesidioblastosis." (PMID 35115561, 2022). "We herein describe an unusual case of adult-onset nesidioblastosis coexisting with an insulin-secreting pancreatic adenoma." (PMID 32047477, 2020). "Here we describe an unusual case of adult-onset nesidioblastosis coexisting with an insulin-secreting pancreatic adenoma." (PMID 32047477, 2020). "In Proye report, 1 nesidioblastosis patient recurred 3 months postoperatively, even though the intraoperative blood glucose returned to normal levels, but with high portal vein insulin levels." (PMID 27367988, 2016). "In our series, this procedure also allowed the diagnosis of three cases of nesidioblastosis, showing a rise in insulin secretion in several pancreatic arteries, especially in the head of the pancreas where the most islet mass is located." (PMID 27795707, 2016). "In our study, the ASVS, evaluated as a functional and morphological technique, was the procedure that allowed the confirmation of pathological insulin production due to a pancreatic mass or islet hyperplasia as in nesidioblastosis." (PMID 27795707, 2016). "Those cases where standard imaging techniques could not detect a solitary lesion and during ASVS equally increased insulin concentrations were obtained by calcium stimulation on more than one supplying artery, were considered nesidioblastosis." (PMID 39497809, 2024). "We found comparably marked insulin elevation in two of the nesidioblastosis cases." (PMID 39497809, 2024). "However, upon glucose administration, there was a remarkable increase in the calcium response in nesidioblastosis-derived cells, which consecutively led to higher insulin secretion." (PMID 37371827, 2023). "Thus, the CACNA1C gene is a promising candidate for screening in patients with dysregulated insulin secretion, e.g., congenital hyperinsulinism (CHI)." (PMID 35897673, 2022). "The pathophysiology of PPH remains unclear with multiple mechanisms suggested including nesidioblastosis, altered insulin clearance and increased glucagon-like peptide-1 (GLP-1) secretion." (PMID 28855269, 2017). "The results showed that even when all the insulin-releasing cultures presented very low migration, the motility of the neoplastic cells was very low, and surprisingly, this ability increased in hyperplastic (nesidioblastosis)-derived VGA cells." (PMID 19545371, 2009).